CD14 (CD14 molecule)
Diseases named in the same sentence as CD14 in open-access papers (continued):
Sharing a sentence is not in itself a finding about the gene and the disease.
liver fibrosis (continued). "Mechanistically, Dectin-1 activation led to the downregulation of TLR4 and its co-receptor CD14, thereby undermining TLR4 signaling in hepatic stellate cells and inhibiting liver fibrosis and oncogenesis." (PMID 39590166, 2024). "We have done this through the measurements of markers of endotoxin exposure such as soluble CD14 (sCD14) and LPS binding protein (LBP) in patients with varying levels of liver fibrosis." (PMID 23750224, 2013). "CD14+ and CD16+ EVs show potential capacity to predict liver fibrosis severity." (PMID 36555854, 2022). "Development of LPS mimetics that do not engage CD14/TLR4 but still can act on activated HSCs will be a novel way to reverse these cells to the non-fibrogenic phenotype for treating liver fibrosis." (PMID 32373617, 2020). "Most of the patients in our study did not have any liver fibrosis, but the CD14-mid, CD32-high and CD14-high, CD32-mid Kupffer cell subsets were present in almost all patients' liver tissue." (PMID 33101269, 2020). "Classical (CD14++CD16−) and intermediate monocytes (CD14++CD16+) are generally considered to have inflammatory properties similar to murine Ly6Chi monocytes in liver fibrosis, whereas nonclassical monocytes (CD14+CD16++) display patrolling properties similar to murine Ly6Clo monocytes." (PMID 41479922, 2025). "This indicates that IL-8, especially from ‘non-classical’ CD14+CD16+ monocytes, might contribute to amplify inflammatory signals in liver fibrosis." (PMID 21731723, 2011). "Furthermore, compared with the antifibrotic effects of PNS on DIO mice, PNS had less effective action on hepatic fibrosis in ob/ob mice, which might be due to the negative influence of PNS on CD14 and TLR4 activation." (PMID 33656663, 2021).
Cirrhosis (33 papers, 2010 to 2025). A chronic disorder of the liver in which liver tissue becomes scarred and is partially replaced by regenerative nodules and fibrotic tissue resulting in loss of liver function. "We newly describe the expansion of an AXL-expressing immune-regulatory monocyte subset (CD14+HLA-DR+AXL+) along cirrhosis progression and its close association with disease severity, infection susceptibility, development of AD, and prognosis." (PMID 31822557, 2020). "Patients with cirrhosis due to viral hepatitis showed increased numbers of hepatic macrophages associated with the infiltration of other pro-inflammatory CD14+HLA-DRhiCD206+ myeloid cells, which in turn produced pro-inflammatory cytokines such as IL-1β, IL-18, and TNF-α." (PMID 36926073, 2022). "Patients with hepatitis and cirrhosis presented increased CD14 +CD16+ macrophages in liver tissue samples." (PMID 38473721, 2024). "In cirrhosis, CD14+CD16+ monocytes increase, expressing more TNF, determining a pro-inflammatory and profibrogenic phenotype." (PMID 38473721, 2024). "AXL and MERTK expression on circulating monocytes modulated immune responses in patients with cirrhosis (CD14+HLA-DR+AXL+) and acute-on-chronic liver failure (CD14+MERTK+)." (PMID 37004869, 2023). "Following pathological BT in patients with decompensated cirrhosis, CD14+TREM1+iNOS+ intestinal monocyte-derived macrophages were recruited from the circulation into the duodenum via MCP-1 secreted by intestinal epithelial cells." (PMID 36926073, 2022). "Previously, a subset of CD14loCD16- tissue resident KCs were found in the liver of cirrhosis patients, while CD14hiCD16- and CD14+CD16+ macrophages are defined as monocyte derived macrophages in humans." (PMID 35990625, 2022). "One study identified an activated CD14+TREM1+ intestinal macrophage phenotype in cirrhosis, with high expression of iNOS even in early compensated disease and secretion of NO." (PMID 33868313, 2021). "We observed increased plasma soluble CD14 (sCD14), a co-receptor for LPS (endotoxin) released by monocytes upon activation in patients with decompensated cirrhosis compared with HVs." (PMID 34825153, 2021). "recently identified a distinct immune-regulatory population of (CD14+HLA-DR+) AXL-expressing monocytes that is expanded in parallel with progression of cirrhosis prior to the AD/ACLF stage and correlates with development of infection and one-year mortality." (PMID 33868313, 2021). "To investigate the effect of the expanded CD14+HLA-DR+AXL+ subset on the impaired inflammatory cytokine responses observed in monocytes from patients with cirrhosis we assessed the functional properties of AXL+ monocytes ex vivo." (PMID 31822557, 2020). "Although CD14+HLA-DR+AXL+ cells accumulated with worsening stages of cirrhosis, they disappeared upon acute hepatic decompensation." (PMID 31822557, 2020). "By contrast, CD14+HLA-DR+MERTK+ monocytes remained undetectable in stable cirrhosis and emerged upon AD." (PMID 31822557, 2020). "AXL+ monocytes showed preserved phagocytosis capacities for E. coli bioparticles and live E. coli bacteria, whereas M-MDSCs revealed reduced phagocytosis, when compared with CD14+HLA-DR+AXL− monocytes from patients with cirrhosis and HC." (PMID 31822557, 2020). "The aim of our study was to assess a possible association between plasma inflammatory biomarkers (CRP, IL-6, soluble CD14) and the extent of fibrosis or cirrhosis using a FibroScan® in HIV/HCV co-infected patients." (PMID 23527135, 2013). "Accordingly, the surface HLA-DR expression on CD14+HLA-DR+ monocytes was markedly reduced in patients with cirrhosis as shown by a decreased mean fluorescence intensity (MFI)." (PMID 23446058, 2013). "We selected 8 patients with advanced cirrhosis for analyzing the genes of CD1c+ or CD14+ cells involved in the regulation and enzymatic pathways of the TCA cycle." (PMID 24322372, 2013).
Cirrhosis (continued). "Elevated CD169+CD14+ myeloid cells help to further explain that the mechanisms of type I IFN are critical in inducing systemic inflammation and immune deficiency in patients with cirrhosis." (PMID 38413535, 2024). "And CD14+CD16+ macrophages are the most abundant in cirrhosis livers." (PMID 35990625, 2022). "Importantly, the CD14+HLA-DR+AXL+ immune cell subset detailed here has to be distinguished from the recently identified immunosuppressive M-MDSCs in patients with cirrhosis and ACLF, which we observed expanding from Child A to C in our cohort." (PMID 31822557, 2020). "Our results suggest that bacteria may have a role as inducers of the CD14 mediated inflammation process that may lead to fibrosis and cirrhosis." (PMID 24564202, 2014). "Our group has previously reported a link between alcoholic liver cirrhosis and bacterial recognition receptor CD14 genetics supporting the hypothesis of the involvement of intestinal bacteria and their endotoxins in the pathogenesis of cirrhosis." (PMID 24564202, 2014). "However, we did not observe a significant correlation of HLA-DR expression on CD14+ monocytes with liver function or stage of cirrhosis or circulating IL-10 levels." (PMID 23446058, 2013). "Finally, we confirmed that the TNF-alpha mRNA of CD14 monocytes, isolated from patients with advanced cirrhosis, was at a higher level than in healthy controls." (PMID 21858100, 2011). "Our study, comprising 226 patients with chronic liver diseases (CLD) at various stages of fibrosis/cirrhosis from different disease etiologies and 184 controls, demonstrates that circulating monocytes increase during disease progression, specifically the CD14+CD16+ subset." (PMID 20548789, 2010). "Furthermore, genes typically expressed by monocytes/macrophages, CD14 and Irf7, were overexpressed throughout the course of liver injury with further elevation of CD14 in advanced cirrhosis compared to both inflammation and cirrhosis time points (P = 0.037 and P = 0.041, respectively)." (PMID 33858327, 2021). "Moreover, in patients with cirrhosis and ascites, the CD14highCD16high peritoneal macrophage subset represented approximately 30% of total CD14+ cells, compared with approximately 15% in women undergoing gynaecological surgery, perhaps reflective of the enhanced BT in cirrhosis." (PMID 33868313, 2021). "Immune cells obtained from ascites of four patients with cirrhosis were profiled using a panel of markers to enumerate T cells (CD3+, CD4+, CD8+), B cells (CD19+), monocytes/macrophages (CD14+), natural killer (NK) cells (CD16+CD56+), and neutrophils (CD15+)." (PMID 38474048, 2024). "When shown by group, the scRNA-seq data revealed a significant increase of Mono/Mac (clusters 2, 7, 8 and 17 which were CD14 and CD68 co-expressed) in the ACLF group compared with the cirrhosis group." (PMID 37380987, 2023). "The reduced HLA-DR expression on monocytes in cirrhosis was associated with the expansion of mononuclear myeloid-derived suppressor cells (M-MDSC, CD11b+CD14+HLA-DRlo/−CD15−) in the circulation of patients with cirrhosis." (PMID 36926073, 2022). "Seven DEGs (TYMP, TYROBP, CD14, TGFBI, LILRA2, GNLY, and GZMB) were common to HCC, cirrhosis, and CHB when compared to healthy controls." (PMID 35265561, 2022). "Detailed analyses of the distinct subsets revealed that TNF-α/IL-6 production in response to LPS was decreased in both CD14+HLA-DR+AXL+ monocytes and M-MDSCs when compared with CD14+HLA-DR+AXL− monocytes from patients with cirrhosis and HC." (PMID 31822557, 2020). "Compared to healthy controls, patients with cirrhosis had higher circulating levels of LBP and IL-10, an expansion of peripheral blood CD14+ monocytes with low HLA-DR expression and an increased fraction of CD25-positive CD4+ and CD8+ T cells." (PMID 23446058, 2013).
Cirrhosis (continued). "We used a serum-free culture medium consistent with the average concentrations of plasma amino acids from patients with advanced cirrhosis (ACM), and examined the function of CD14+ monocytes or THP-1 under ACM that contained 0–300 nmol/mL L-Cys with LPS." (PMID 21858100, 2011). "Strikingly, we observed a strong shift towards the CD14+CD16+ monocyte subset in CLD patients, especially in patients with established cirrhosis." (PMID 20548789, 2010). "In our cohort of patients with cirrhosis and ACLF, HLA-DR expression on CD14+ myeloid cells strongly negatively correlated with established scores of liver disease severity Child-Pugh, MELD, CLIF-SOFA, NACSELD score (r=−0.53, p<0.001, n=98) and also SIRS score (r=−0.46, p<0.001, n=96)." (PMID 28592438, 2018). "In patients with chronic liver diseases and cirrhosis, non-classical CD14+CD16+ monocytes exert pro-inflammatory and pro-fibrogenic actions." (PMID 23259611, 2012). "This suggests that the proposed pro-inflammatory and profibrogenic actions of CD14+CD16+ monocytes/macrophages are most relevant at advanced fibrosis or cirrhosis, possibly explaining different observations between human cirrhosis and experimental mouse models." (PMID 20548789, 2010). "The CD14+HLA-DR+AXL− population represented the majority of monocytes in HC, indicating it may be regarded “functionally intact” but was sequentially lost in the circulation of patients with progression of cirrhosis." (PMID 31822557, 2020). "LBP as a marker for bacterial translocation was not different in the four groups, but soluble CD14 (sCD14) was significantly elevated in SC-CIP and cirrhosis compared to healthy controls (p < 0.001) and in cirrhosis compared to CIP controls (p = 0.01)." (PMID 32906634, 2020). "CD14 selection has no appreciable adverse effect on function such as response to TLR ligation or CD40 ligation and yielded cells efficient at reversing cirrhosis in experimental models." (PMID 28673774, 2017). "Interestingly, the numbers of CD14 + + CD16+ intermediate and CD14 + CD16 + + nonclassical monocytes were greater in the livers of participants with T2D and NASH or liver cirrhosis than in those of participants with T2D but no NASH or cirrhosis." (PMID 37735474, 2023).
hepatocellular carcinoma (33 papers, 2010 to 2024). A malignant tumor that arises from hepatocytes. "ALDH2, ITGB2, LGALS3, CTSB, PRDX1, and CD14 were identified as multifunctional proteins that are associated with tumorigenesis, damage, cancer cell death, necrosis, fibrosis, hepatocellular carcinoma, steatosis, and inflammation." (PMID 29481576, 2018). "Although marked increases in CD14 mRNA caused by LPS stimulation have been observed in vivo, only modest increases in CD14 mRNA levels and promoter induction are caused by exposure to LPS in rat hepatoma cells." (PMID 22511970, 2012). "The study found that the chemokine CCL15 recruits CCR+ CD14+ monocytes in hepatocellular carcinoma, driving multiple tumor-promoting factors." (PMID 38075694, 2023). "In accordance with our study, other group reported that the frequency of circulating CD33+HLA-DRlow/−CD11b+CD14+PD-L1+MDSCs increased in hepatocellular carcinoma (HCC) patients versus controls." (PMID 32487171, 2020). "(a) CD14+ cells isolated from patients with hepatocellular carcinoma (HCC) were classified into four subgroups (PD–L1+PD–L2+ CD14+ cells, PD–L1+PD–L2− CD14+ cells, PD–L1−PD–L2+ CD14+ cells and PD–L1−PD–L2− CD14+ cells)." (PMID 32587357, 2020). "Hepatic carcinoma related tumor-associated fibroblasts (TAFs), a stromal part in HCC, can induce peripheral blood monocyte migration and differentiation into CD14 + HLA-DR −/low MDSCs by SDF-1α." (PMID 31500650, 2019). "In hepatocellular carcinoma, the basal level of CD14+HLA−DR−/low MDSCs is higher than that in healthy controls." (PMID 28603525, 2017). "Flow cytometry as well as confocal laser scanning microscopy (CLSM) showed that PLGA/PEI NPs are more readily taken up than PLGA NPs by both human CD14+ monocytes and mouse Hepa 1–6 hepatoma cell line." (PMID 26444005, 2015). "On the other hand, human M-MDSCs have been described as CD14+HLA-DR−(CD33+Lin−) in hepatocellular carcinoma, metastatic prostate cancer, renal cell cancer, and malignant melanoma." (PMID 26078490, 2015). "CD14+HLA-DR−/lo M-MDSCs inhibit NK cell cytotoxicity and cytokine secretion in a cell-contact-dependent manner in human hepatocellular carcinoma." (PMID 26078490, 2015). "IL-6 has been shown to regulate (increase) CD14 expression and synthesis in both HepG2 hepatocellular carcinoma cells and in human primary hepatocytes." (PMID 22970235, 2012). "It has been reported that CD14+HLA-DR–/low M-MDSCs could induce CD4+CD25+Foxp3+Treg cells when co-cultured with autologous T cells in hepatocellular carcinoma (HCC) patients." (PMID 33384962, 2020). "In addition, high percentages of CD14+HLA-DR−/low M-MDSCs in patients with hepatocellular carcinoma were shown to induce the production of CD4+CD25+Foxp3+ regulatory T cells." (PMID 25436215, 2014). "Here, we analyze the percentage of CD14+CXCR2+ monocyte subsets in hepatocellular carcinoma (HCC) patients, and investigate the mechanisms that regulate CXCR2 surface expression on monocytes and its biological function." (PMID 37403022, 2023). "Monocytes (CD14+ cells) from advanced-stage hepatocellular carcinoma (HCC) patients express programmed death 1 ligand (PD-L)/PD-1 and suppress the host antitumor immune response." (PMID 32824016, 2020). "Four genes, CD14, NPC2, IER3, and GZMA, have been extensively investigated in hepatocellular carcinoma." (PMID 37354485, 2023). "This is in line with previous data on hepatocellular carcinoma showing that tumor infiltrating CD169+ macrophages originate from monocytes, and a study where CD169+CD14+ TAMs were characterized using CyTOF." (PMID 37404831, 2023). "In human hepatocellular carcinoma, most abundantly expressed CCL15 recruited CCR1+ CD14+ monocytes toward HCC invasive margin to enhance tumor metastasis by inducing immune suppression and angiogenesis." (PMID 35267547, 2022).
hepatocellular carcinoma (continued). "Finding that PCV1 is able to infect CD4+, CD8+, CD14+, CD19+ and CD56+ human cells, and the observation of productive PCV1 infection in a subclone of a human hepatocellular carcinoma cell line suggests potential risks for humans." (PMID 29165219, 2018). "Radiotherapy significantly reduced the frequency of CD14+HLA−DR−/low MDSCs that was negatively correlated to patient overall survival, indicating that a reduction of MDSCs after radiotherapy could be used as a prognostic factor in hepatocellular carcinoma patients." (PMID 28603525, 2017). "For example, fucosylated APOH, CD14 and ICAM1 were detected with a high level in plasma of patients with human hepatocellular carcinoma (HCC) and fucosylated ICAM1 may represent a good prognostic marker for HCC." (PMID 34199928, 2021). "However, patients with liver cirrhosis and hepatocellular carcinoma (HCC) even displayed significantly higher CD14+CD16+ monocytes than cirrhotic patients without HCC (p = 0.008)." (PMID 20548789, 2010). "The HG23 replicon cell line derived from the human hepatocellular carcinoma cell line Huh7 normally fails to respond to TLR4 ligands because of the low-level expression of TLR4 expression together with the lack of the expression of its accessory proteins, CD14 and MD26." (PMID 29875467, 2018). "Moreover, in addition to supernatants from HepG2 cells, TSN from other hepatoma cell lines (SK-Hep-1, Hep3B, and PLC/PRF/5), but not supernatants from the normal liver cell line HL-7702, could also induce the upregulation of CA12 in CD14+ cells." (PMID 35362480, 2022).